MTOR (mechanistic target of rapamycin kinase)
Diseases named in the same sentence as MTOR in open-access papers (continued):
Sharing a sentence is not in itself a finding about the gene and the disease.
colon carcinoma (continued). "The findings from the present study suggest that myricetin induces colon cancer cell autophagy and apoptosis by inhibiting PI3K/Akt/mTOR signalling." (PMID 32631392, 2020). "The m6A methyltransferase inhibitor SAH 75 elevated the expression of AKT1, PTEN, mTOR, and PIK3CA in stomach and colon cancer cell lines." (PMID 32863943, 2020). "Asiatic acid can also affect the expression of epithelial-mesenchymal transition marker proteins in colon cancer cells (E cadherin↑, vimentin ↓, N-cadherin↓), achieved this anti-cancer potential by regulating PI3K/Akt/mTOR/p70S6K signaling pathway." (PMID 33013406, 2020). "Collectively, the present results indicated that TDH can inhibit the proliferation vitality of colon cancer LoVo cells through downregulating GOLPH3 expression and activity of PI3K/AKT/mTOR and Wnt/β-catenin signaling pathways." (PMID 32454851, 2020). "In genetic models, low serum APN can promote breast and colon cancer development through angiogenic mechanisms and by modulating the AMPK-activated protein kinase (AMPK)/mammalian target of Rapamycin (mTOR) pathway." (PMID 30794695, 2019). "In the current study, we incubated human colon cancer HCT116 cells with vanillic acid, the results showed that vanillic acid inhibited p-mTOR, p-p70S6K, p-4E-BP1, and p-eIF4E protein expression levels." (PMID 30678221, 2019). "For instance, olfactory receptor OR51B4 is highly expressed in colon cancer HCT116 cells and the activation of the receptor by its ligand (Troenan) inhibited cell proliferation and apoptosis by phosphorylation of p38, mTOR, and Akt kinases." (PMID 31068808, 2019). "Here, we have analyzed the therapeutic potential for the novel, orally available dual PI3K/mTOR inhibitor NVP-BEZ235, which has entered clinical trials with low side-effects of solid tumors, including colon cancer." (PMID 31871431, 2019). "Anticancer activity of adenine in colon cancer cells is attributable to the activation of apoptotic signaling and in turn the AMPK/mTOR pathway." (PMID 31611925, 2019). "Previous studies have suggested that hesperidin induces apoptosis and autophagy through inhibition of PI3K/Akt/mTOR and glycogen synthase kinase-3 beta (GSK-3β) pathways in colon cancer." (PMID 31815144, 2019). "In conclusion, our present study demonstrated that vanillic acid decreases HIF-1α protein synthesis by inhibiting mTOR/p70S6K/4E-BP1 and Raf/MEK/ERK pathways in human colon cancer HCT116 cells." (PMID 30678221, 2019). "FOXO6 is a transcription factor mostly found in the nucleus that has been recently linked to EMT as its silencing has been associated with reduced cell proliferation, migration and invasion in colon cancer cells, via the inhibition of PI3K/Akt/mTOR pathway." (PMID 31293614, 2019). "We have also demonstrated that inhibition of mTOR affects OGT protein level and overall O-GlcNAcylation levels in HCT116 colon cancer cell line." (PMID 30356686, 2018). "Recent findings indicated that curcumin, another hydrophobic polyphenol, enhances autophagic flux both in human colon cancer HCT116 cells and in mouse embryonic fibroblasts (MEFs) via mTOR suppression and increased TFEB transcriptional activity." (PMID 29765503, 2018). "The aim of the in vitro study was to investigate the anticancer activity of InsP6 on colon cancer with the focus on inhibiting the AKT1 kinase and p70S6K1 as mTOR effector, in relation to proliferation and apoptosis of cells." (PMID 28972559, 2017). "The aim of the current study was to investigate the anticancer activity of InsP6 on colon cancer with focusing on inhibiting the AKT1 kinase and p70S6K1 as mTOR effector, in relation to proliferation and apoptosis of cells." (PMID 28972559, 2017). "In fibroblasts, as well as breast and colon cancer cells, stimuli leading to PI3K activation increase HIF-1α protein levels through the downstream activation of Akt and mTOR." (PMID 28401064, 2017).
colon carcinoma (continued). "The second analyzed inhibition target of the PI3K/Akt/mTOR pathway was PI3K in HT29, HCT116, and SW480 colon cancer cells." (PMID 27626684, 2016). "In vitro studies also found that mTOR-siRNA suppressed the growth of esophageal squamous cell carcinoma (ESCC), human colon cancer cells and non-small cell lung cancer cells." (PMID 27911920, 2016). "mTOR inhibitors suppress tumor cell growth and angiogenesis, and have recently been shown to induce death receptor/FADD-dependent apoptosis in colon cancers." (PMID 27351224, 2016). "Pik3caH1047Rresults in activation of the PI3K/AKT/mTOR pathway and ERK 1/2 signaling: The epithelial cells in Fc+Pik3caH1047R and Fc+ Pik3cap110* colon cancers demonstrate increased staining for phosphorylation of RPS6 compared to those in ApcMin colon tumors." (PMID 26863299, 2016). "Metformin is an activator of AMPK and an inhibitor of mTOR, and it decreases the expression of FASN and SREBP1c in colonic tumors from mice fed a high-energy diet." (PMID 26002551, 2015). "In HT29 colon cancer cells, as we previously reported in endothelial cells, phosphorylation of PI3K and its downstream signals, Akt and mTOR phosphorylation, were blocked by SMA." (PMID 26544726, 2015). "The expression of mTOR and pmTOR was analyzed by immunohistochemistry in 106 clinical specimens of stage IIIB colon cancer." (PMID 25120661, 2014). "The aim of the present study was to investigate the significance of aberrant expression of mammalian target of rapamycin (mTOR) and the activated form of mTOR kinase, phosphorylated mTOR (pmTOR), in human stage IIIB colon cancer." (PMID 25120661, 2014). "The expression of mTOR and pmTOR was detected by immunohistochemistry in the tumor tissue of stage IIIB colon cancer patients." (PMID 25120661, 2014). "We further observed that targeting MAPK with a MEK inhibitor in combination with mTOR inhibitors resulted in synergistic inhibition of LS174T and SW480 colon cancer cell growth." (PMID 22401294, 2012). "All these findings re-confirm the in vitro results about the inhibitory effects of AST on tumor angiogenesis that are regulated by modulation of both mTOR and COX-2 signaling in colon cancer cells." (PMID 22992293, 2012). "In this study, we have determined the anticancer activity of PP242, a kinase inhibitor of mTOR and NVP-BEZ235, a dual PI3K/mTOR inhibitor, in colon cancer cells, both in vitro and in vivo." (PMID 22401294, 2012). "In this study, we found that two such inhibitors, PP242, a specific inhibitor of mTOR and NVP-BEZ235, a dual PI3K/mTOR inhibitor, effectively reduced colon cancer cell proliferation and survival and the growth of colon cancer tumor xenografts." (PMID 22401294, 2012). "Downregulation of mTORC2, by either blocking the expression of mTOR or rictor, reduced the proliferation of HT29 and LS174T colon cancer cells in vitro and inhibited the formation of tumor xenografts in vivo." (PMID 20226010, 2010). "Evidence from in vitro, in vivo, and clinical studies highlights their role in suppressing various cancers, including breast, prostate, lung, gastric, and colon cancer, primarily through the regulation of signaling pathways, that is, MAPK/ERK and PI3K/AKT/mTOR." (PMID 40078339, 2025). "For example, an ethanol extract of Glycyrrhiza glabra induces apoptosis in HT29 cells via HSP90 downregulation, while total saponins extracted from Astragalus membranaceus root modulate mTOR and COX-2 signaling, reducing VEGF levels and suppressing angiogenesis in HCT116 colon cancer cells." (PMID 40149916, 2025). "Their clinical relevance in gastric and colon cancers stems from their frequent dysregulation, often driven by genetic alterations (e.g., KRAS, BRAF, PIK3CA, PTEN, and mTOR), which leads to constitutive activation and fosters uncontrolled cancer cell growth and survival." (PMID 40729043, 2025). "Moreover, previous studies have shown that USP15 promotes colon cancer proliferation and invasion via the AKT/mTOR pathway." (PMID 39794359, 2025).
colon carcinoma (continued). "Additionally, apigenin suppresses the mTOR/PI3K/AKT signaling pathway, thereby promoting autophagy in erythroid subtype leukemia (TF-1), liver cancer (Hep G2), and colon cancer (HT-29) cells." (PMID 40490812, 2025). "Given that the inhibitory effects of fisetin on PI3K/AKT/mTOR pathway in colon cancer have not been fully investigated." (PMID 41180483, 2025). "It has been demonstrated that tea polysaccharides may act on the mTOR-TFEB signaling pathway and promote cytotoxic autophagy, which, in turn, inhibits the growth of colon cancer cells." (PMID 39201782, 2024). "SCFAs, could promote cell apoptosis by inhibiting PI3K-Akt signaling in colon cancer cells, and kynurenic acid decreased the phosphorylation of Akt with suppressing PI3K-Akt–mTOR pathway to prevent the growth of colon cancer cells." (PMID 38699473, 2024). "Furthermore, our investigation unveiled diverse cellular and molecular stratifications among colon cancer patients, suggesting that the high-score group derive substantial advantages from dual inhibition of PI3K and mTOR by PI-103." (PMID 38740818, 2024). "Moreover, inhibition of mTOR is accompanied by significantly decreased phosphorylation of 4 E-BP1 and p70S6 in the 3 colon cancer cell lines." (PMID 37808182, 2023). "Similarly, polyphyllin I (PPI) induces ROS production and down-regulates the AKT/mTOR pathway, which in turn triggers the autophagic cell death and apoptosis of SW480 colon cancer cells." (PMID 37373349, 2023). "Our study is the first to confirm that propofol could inhibit the stemness and EMT of colon cancer cells at least partially through, SIRT1, and the Wnt and PI3K/AKT/mTOR signaling pathways." (PMID 37490168, 2023). "Along with the PI3K/AKT/mTOR signaling pathway, the hsa_circ_0008234/miR-338-3p/ETS1 axis may influence the activity of colon cancer malignancy." (PMID 37046729, 2023). "In a first set of experiments, we evaluated the impact of several small molecule inhibitors targeting major signaling hubs of the PI3K/AKT/mTOR and the Ras/RAF/MAPK pathway in DLD-1 colon cancer cells in conventional 2D (3000 cells/well) and 3D spheroid (3000 cells per spheroid) cultures." (PMID 36675180, 2023). "In conclusion, the obtained results exhibited that 5-FU nanogel has an excellent effect rather than the 5-FU which was confirmed by suppressing the proliferation of colon cancer via inhibition of the TLR2/ NF-κβ and PI3K/AKT/mTOR as well as lowering the expression levels of Ki-67." (PMID 37493814, 2023). "In line with this, it has been recently shown that hyper-activated pro-proliferative signaling cascades such as PI3K/mTOR- and MEK-1/ERK-dependent pathways are potently down-regulated in tumor spheroids of colon cancer cells as a large proportion of cells in 3D structures are growth-arrested." (PMID 36849252, 2023). "When mTOR was inhibited by rapamycin or EBSS starvation, EN failed to decrease the autophagy level of colon cancer cells, confirming the importance of mTOR in mediating autophagy." (PMID 35889271, 2022). "In conclusion, our experimental evidence confirmed that AC may suppress the growth and liver metastasis in colon cancer by regulating EMT via the CXCL8/CXCR2 axis and PI3K/AKT/mTOR signaling pathway." (PMID 35922850, 2022). "In colon cancer, SNX10 has been proved to regulate expression of a core effector, P21, in tumor suppressing pathways and to affect metabolism of amino acids mediating activation of mTOR by regulating chaperone-mediated autophagy." (PMID 35715463, 2022). "Taken together, these results suggested that AC may down-regulate CXCL8/CXCR2 chemokine axis and suppressing the PI3K/Akt/mTOR pathway to inhibit the EMT process, thus acting on its anti-liver metastasis effect in colon cancer." (PMID 35922850, 2022).
colon carcinoma (continued). "A study focused on the TME in colon cancer observed that co-culturing macrophages with colon cancer cells stimulated the release of epidermal growth factor (EGF) in CRC cells, which activated the EGFR/PI3K/AKT/mTOR signaling pathways, resulting in a polarization of TAMs into M2 phenotype." (PMID 35912261, 2022). "Importantly, the PI3K/mTOR inhibitor NVP-BEZ235 effectively reversed 5-FU resistance through inactivation of PI3K/Akt, which led to enhanced levels of FOXO3 in colon cancer cells." (PMID 35910798, 2022). "For example, Bacteroides could promote colon cancer progression via inducing the stemness of colon cancer cells and activating RHEB/mTOR signaling pathway." (PMID 35592677, 2022). "The MTOR/RIPK3/necroptosis axis is an initiator of IBD and colon cancer." (PMID 35884370, 2022). "The levels of phospho-mTOR (Ser2448), a downstream target of both AMPK and Akt, decreased in AT1.6 and AT6.4 cells but increased in BR colon cancer cells compared to that of their respective PT cells or returned to the basal level of PT cells in BR colon cancer cells." (PMID 34829834, 2021). "However, we showed that fargesin inhibited EGF-induced phosphorylation levels of mTOR and AKT in JB6 Cl41 premalignant and WiDr and HCT8 colon cancer cells." (PMID 33669811, 2021). "Activation of AMPK restored sensitivity to butyrate by the inhibition of Akt/mTOR, suggesting that AMPK could be a therapeutic target for BR colon cancers." (PMID 34829834, 2021). "Furthermore, a study has reported that the Akt-mTOR signaling pathway which is known to be regulated by ILK is also involved in angiogenesis in colon cancer." (PMID 34163519, 2021). "A study on the effect of mTOR on VEGF showed that everolimus reduced human VEGF secretion by 20–45% in wild type and resistant cancer cell lines including GEO and GEO-GR (gefitinib resistant) colon cancer." (PMID 33925400, 2021). "Although there are few studies in colon cancer showing direct angiogenesis induction by ILK, one report has revealed that ILK overexpression regulates mesenchymal stem cell survival and angiogenesis via Akt and mTOR phosphorylation and VEGF expression." (PMID 34163519, 2021). "In the same manner, when the mTOR/SGK1 axis is blocked and colon cancer cells are stressing with ROS accumulation, this could induce autophagy to precede apoptosis, so one process depends on each other." (PMID 34123772, 2021). "One study reported that hesperidin treatment could induce apoptosis and trigger autophagy by inhibiting the aurora-a mediated PI3K/Akt/mTOR and glycogen synthase kinase 3 beta (GSK-3β) pathway in colon cancer mouse model." (PMID 34830339, 2021). "In order to explore whether the autophagy induced by chronic exposure with respect to butyrate was related to AMPK/ACC and Akt/mTOR signaling pathways, immunoblot analysis was performed in PT, AT1.6, AT6.4, and BR colon cancer cells of HCT116, HT29, and SW480." (PMID 34829834, 2021). "In human colon cancer cells, noscapine induces apoptosis via enhanced PTEN/PI3K/mTOR signaling." (PMID 34094892, 2021). "In vitro experiments, adiponectin inhibits colon cancer cell growth in adiponectin receptor (AdipoR1- and -R2) positive HCT116, HT29, and LoVo cells through the AMP-activated protein kinase (AMPK)/mammalian target of rapamycin (mTOR) signaling pathway." (PMID 32486076, 2020). "Strikingly, these results were confirmed in vivo not only in a mouse xenograft model where coordinated autophagy and mTOR inhibition induced tumor remission only in HIF-2α-silenced cells, but importantly, were also confirmed in patient-derived primary colon cancer cells." (PMID 31151160, 2019). "Interestingly, we found that many of the DEGs and their regulators were prognostic markers for colon cancer, including CEBPB, PPARGC1, STAT3, MTOR, BCL2, JAK2, and CDK1." (PMID 31186640, 2019). "In the colon cancer model, H2S regulates AMPK/mTOR pathway to induce protective autophagy." (PMID 31708756, 2019).
colon carcinoma (continued). "The results showed that increased phosphorylation of AMPK in both colon cancer cell lines treated with adenine were restored in the presence of AMPK inhibitor, dorsomorphin, at a concentration of 5 μM corresponding with increased mTOR phosphorylation." (PMID 31611925, 2019). "DB-medicated CSC-inhibitory effects were associated with the decreased expression of the IGF downstream oncogenic marker, mTOR/STAT3, as well as the stemness marker, β-catenin, both of which have been reported to contribute to treatment failure and the recurrence of colon cancer." (PMID 30257507, 2018). "Increased O-GlcNAcylation in colon cancer cells, either by OGT overexpression or OGA inhibition, reduces phosphorylation of AMPK at Thr172, activates mTOR and induces cell growth in vitro in LoVo cell line and in vivo in LoVo cell-derived tumors of BALB/c-nu/nu mice." (PMID 30356686, 2018). "We have confirmed that O-GlcNAcylation activates mTOR in HCT116 colon cancer cell line but not in CCD841CoN normal cells." (PMID 30356686, 2018). "Studies by Yang F and Gao JY showed that inhibition of PI3K/Akt/mTOR pathway by an inhibitor (BEZ235) or PI3KCA knockdown (shRNA transduction) significantly suppressed cell proliferation, migration, invasion and induced apoptosis human colon cancer cells." (PMID 29439667, 2018). "In vitro, this adipokine is able to activate the phosphoinositide 3-kinase (PI3K)/protein kinase B (PKB/AKT)/mammalian target of rapamycin (mTOR) signaling pathway and therefore enhance proliferation and inhibit apoptosis of the human HCT116 colon cancer cells." (PMID 28632155, 2017). "In the present study, we demonstrated the suppressive effect of InsP6, a natural occurring phytochemical, on the expression and activity of key components of the AKT/mTOR signaling axis including AKT1 and p70S6K1 in colon cancer cells as significant regulators of proliferation and apoptosis." (PMID 28972559, 2017). "Studies have shown that miR-144 can also suppress the expression of the tumor suppressor, phosphatase and tensin homolog (PTEN) and mammalian target of rapamycin (mTOR) and inhibit the growth of colon cancer cells in a Notch-1-dependent manner." (PMID 26826553, 2016). "Aberrant activation of PI3K/Akt/mTOR and MAPK/ERK pathways may induce colon tumor growth and progression by increasing β-catenin and cyclin-D1 expression." (PMID 27895803, 2016). "In conclusion, the present study demonstrated for the first time, to the best of our knowledge, that fucoidan inhibited cell growth, migration and sphere formation by suppressing the PI3K/Akt/mTOR pathway and reducing the expression of MMP-2 in human HT-29 colon cancer cells." (PMID 25998232, 2015). "MiR-373 is an oncogene and can induce tumor initiation and progression in testicular germ-cell tumors by targeting tumor suppressor LATS2, and invasion and metastasis by targeting CD44, RECK, mTOR and SIRT1 in breast, colon cancer and fibrosarcoma, respectively." (PMID 26258411, 2015). "By contrast, mTOR and pmTOR were not expressed in the normal mucosa samples obtained from colon cancer patients." (PMID 25120661, 2014). "To next address whether targeting MEK/MAPK signaling pathway would enhance the anticancer activity of mTOR inhibitors, we treated LS174T and SW480 colon cancer cells with U0126, a MEK inhibitor, in combination or not with mTOR inhibitors." (PMID 22401294, 2012). "Indeed, in colon-cancer-bearing mice, protein synthesis was promoted and CSA was preserved in response to aerobic exercise, through the activation of protein kinase B (Akt)/mammalian target of rapamycin (mTOR) signalling, a well-established molecular pathway that regulates protein turnover." (PMID 38136400, 2023).